ENSG00000269564 (novel transcript)
Gene: Long non-coding RNA gene on chromosome 19 (53,786,928 to 53,789,168, forward strand). Ensembl gene ENSG00000269564.
Gene Ontology:
Biological process: miRNA-mediated post-transcriptional gene silencing